Y_RNA (Y RNA )
Gene: Miscellaneous RNA gene on chromosome 12 (120,504,571 to 120,504,659, reverse strand). Ensembl gene ENSG00000222601.
Homologues: Orthologues: chimpanzee Y_RNA (100% identical), macaque Y_RNA (87% identical). Paralogues in human: RNY4 (87% identical), RNY4P9 (87% identical), RNY4P6 (85% identical), RNY4P7 (85% identical), RNY4P25 (84% identical), Y_RNA (84% identical), RNY4P10 (83% identical), RNY4P19 (83% identical), Y_RNA (83% identical), RNY4P27 (82% identical), Y_RNA (82% identical), RNY4P13 (81% identical), and 87 more.